MUC1 (mucin 1, cell surface associated)
Diseases named in the same sentence as MUC1 in open-access papers (continued):
Sharing a sentence is not in itself a finding about the gene and the disease.
cancer (continued). "MUC1-CD is modified by RTKs at the cell membrane and interacts with effectors of the IKK→NF-κB pathway in integrating chronic inflammation with cancer progression." (PMID 38740827, 2024). "In a non-small cell lung cancer (NSCLC) model, a therapeutic combination of CAR T-cells targeting prostate stem cell antigen (PSCA) and mucin 1 (MUC1) effectively eradicated cancer cells expressing PSCA and MUC1." (PMID 38612592, 2024). "Among MUC1-positive OTSCCs in stage III and IV, 63.6% (21/33) and 48.5% (16/33) of patients had MUC1-positive cancer cell rates of more than 50% and 80%, respectively." (PMID 38390321, 2024). "Therefore, inhibiting the activity of MUC1 could be an effective approach in cancer treatment." (PMID 39491020, 2024). "Potential strategies to target Tn for cancer therapy include monoclonal antibodies, therapeutic vaccination, and engineered CAR T cells against Tn antigen on MUC1." (PMID 36725887, 2023). "Epigenetic regulation of mucin expression, such as MUC1, MUC2, MUC4, MUC5AC and MUC17, has been reported to be controlled by DNA methylation in a variety of cancer cells." (PMID 36778111, 2023). "MiRNA 24-3p promoted cancer cell growth and invasion, and it inhibited apoptosis by targeting menin and SRY-related HMG-box genes (SOX 7) gene miRNA 512-3p inhibit the Mucin 1 (MUC1) gene." (PMID 37692575, 2023). "Deregulated expression of other mucins, such as MUC1, MUC2, MUC3, MUC6, MUC17, and MUC20, has also been reported in different cancers, either in their native or post-translationally modified forms." (PMID 36980526, 2023). "The role of MUC1 in the EMT process, which enables cancer cells to become invasive and metastatic, has been directly proven by several studies." (PMID 37581476, 2023). "MUC1, MUC2, MUC5AC and MUC6 were the most commonly analysed mucins across all three cancer types according to this literature review." (PMID 37958425, 2023). "At the same time, the expression patterns of mucins, including MUC1 and MUC2, were found to be different from those of the surrounding concomitant cancer tissues." (PMID 37337182, 2023). "The cancer vaccines administered target a cascade of TAAs, including CEA, MUC1, brachyury, HER2, and RAS." (PMID 36679991, 2023). "The findings suggested that the anti-MUC1 apt/KG6E is internalized readily in A549 cells through a MUC1 recognition that can aid in targeted cargo delivery and detection of cancer tissues." (PMID 37149607, 2023). "In conclusion, the co-delivery of MUC1 and TLR agonists via C3-liposomes greatly enhances the immune response to MUC1, highlighting its potential for antigen-specific cancer immunotherapy." (PMID 38140114, 2023). "MUC1-transduced CT26 colon and TA3HA breast murine cancer cell lines secreted Tu-sEVs that successfully expressed target antigen MUC1 (MUC1-Tu-sEVs)." (PMID 37681880, 2023). "By dissecting cancer gene expression driven by the truncated TG2 isoform and the canonical one, an unbiased new link between TG2 and MUC1 has been established and regulation of MUC1 via transcriptional repression of AR by TG2 revealed for the first time." (PMID 37160910, 2023). "It has been reported that the abnormal expression of Mucin 1 (MUC1), a high molecular weight membrane glycoprotein, can represent a potential cancer marker." (PMID 36683059, 2023). "MUC1 is a highly relevant TAA given its overexpression and hypo-glycosylation in a majority of cancers, and was ranked second among 75 candidate antigens for cancer vaccines by the National Cancer Institute in 2009." (PMID 38140114, 2023). "Previous research has shown that MUC1 or its partial released fragment, KL6 plays a role in anti-inflammatory reaction specially in diseases such as COPD and cancer." (PMID 36959848, 2023).
cancer (continued). "Mucin 1 (MUC-1) is a transmembrane protein mainly expressed in epithelial and hematopoietic cells with aberrant expression in various types of cancer." (PMID 36899934, 2023). "Then, SN38/Exo was conjugated with anti-MUC1 aptamer (SN38/Exo-Apt), and its targeting ability and cytotoxicity towards cancer cells were investigated." (PMID 37009014, 2023). "MUC1 on cancer cells has been reported to bind to SIGLEC9 on macrophages to re-educate the macrophages and help release factors linking to TME and cancer progression." (PMID 36688997, 2023). "The expression of TF antigen in MUC1 was also demonstrated to be important in the regulation of GAL-4- and GAL-8-mediated cancer-endothelium adhesion." (PMID 37898403, 2023). "Understanding how MUC1 can be stabilised by TG2 and the relevance in cancer immune evasion will clarify the full significance of this new finding." (PMID 37160910, 2023). "This unique mechanism supports the non-redundant role of MUC21 in cancer immune surveillance as it is distinct from MUC1, which shows a highly correlated expression with MUC21 in NSCLC and has an intracellular activity in cancer cells." (PMID 37858248, 2023). "Currently, there are two malignancy-specific antigens involved in cancer vaccine therapy: Wilms’ tumor gene antigen (WT1) and mucin 1 (MUC1)." (PMID 37376451, 2023). "For instance, MUC1, MUC5AC, MUC17, and CA19-9 are expressed in carcinomas originating from the conventional pathway, whereas carcinomas originating from serrated pathways do not express these mucins." (PMID 36980526, 2023). "There are two cancer-related antigens used in vaccine therapy, namely Wilms' tumor gene (WT1) antigen and mucin 1 (MUC1) 68, which is mainly a DNA-binding transcription factor and is present in 80% of biliary tract tumors." (PMID 35069894, 2022). "Increased expression levels of HLF, shown to promote cell-cycle progression in various cancers, ITGA2, MUC1, and DPY19L1 have also been proposed to confer prognostic value for the survival of patients suffering from LUAD malignancies." (PMID 36551790, 2022). "Other regulators such as FOXK1, MUC1, PGC-1α, SRC are reported to be involved in miR-485-5p-mediated inhibition of cancer cell proliferation, migration and invasion." (PMID 35706019, 2022). "Over the past decades, many aptamers that specifically target cancer cells have been successfully selected, including AS1411 (nucleolin-targeted), MUC1 (MUC1-targeted), and Sgc8 (protein tyrosine kinase-7-targeted), among others." (PMID 35334728, 2022). "The massive expression of MUC1 and EGFR demonstrated the purity of cancer cells in the organoid-derived xenograft model." (PMID 36340504, 2022). "Therefore, antibodies that are designed to target epitopes within the MUC1 core peptide or the altered glycopeptide epitopes are more likely to bind to tMUC1, and not to MUC1, on normal cells, thus rendering them an attractive candidate molecule for cancer-specific immunotherapies." (PMID 36457849, 2022). "The CAR.MUC1-41BBζ and CAR.MUC1-CD28ζ T cells showed antitumor activity against two MUC1+ cancer cell lines in a dose-dependent manner, indicating a specific antigenic response of the two CAR constructs." (PMID 36457849, 2022). "We also confirmed the cancer-promoting function of HILPDA and MUC1 and the ferroptosis-resistant related mechanism of MUC1 in OS, which suggested that MUC1 has the potential to become a ferroptosis-related therapeutic target." (PMID 36439512, 2022). "Based on previously published data and the results of our study, we suggest that the use of MUC1 and MAGE-A3 in combination with TNF-α is a more reliable approach to generate autologous dendritic cells for basic research on cancer immunology." (PMID 35589776, 2022). "E-selectin recognizes various glycoprotein ligands expressed on cancer cells, including a specific sialofucosylated glycoform of CD44, PSGL1, CD24, MUC1 and LGALS3BP." (PMID 35918322, 2022).
cancer (continued). "MUC1 is another potential candidate that is aberrantly overexpressed in NSCLC and other cancer types." (PMID 35720364, 2022). "The extend of anti‐MUC1 nanobody internalization in MCF‐7 and T47D cell lines was analyzed by examining enhancement in cancer cells fluorescent intensity at predetermined time points (15, 45, and 90 min)." (PMID 34694686, 2022). "Antigen-based cancer vaccines are also used, such as CV301, which targets mucin-1 (MUC-1) and carcinoembryonic antigen (CEA) 2, two major antigens in malignant pancreatic tumors." (PMID 35743107, 2022). "These include: CDH1, MUC1, THBS4, and MSLN for PEs related to cancer; ADA2, CXCL10, and WARS for TB-PEs; CRP, S100A9, and VIM for parapneumonic PEs; and C9, LDHA, HPX, LDHB, and C3 for benign-PEs." (PMID 35197508, 2022). "MUC1 is overexpressed in more than 80% of PDA cases and TGF-β signaling plays an important oncogenic role in majority of cancers especially in PDA (Massagué, 2008)." (PMID 35237602, 2022). "The probe offered improved detection precision in early cancer diagnosis, having a limit of detection (LOD) of 0.13 and 4.50 nM for miRNA-21 and MUC-1, respectively." (PMID 35055294, 2022). "Additionally, CTRP (Cancer Therapeutics Response Portal) database was applied to detect the drug sensitivity of MUC1 and related glycosyltransferases to numerous clinical chemotherapeutics and found most of them were positively corelated with drug resistance, especially MUC1, GCNT3, and GALNT5." (PMID 35970845, 2022). "Transmembrane mucins such as MUC1 and MUC16 are also thought to facilitate the metastasis of many carcinomas by binding to mesothelin in recipient tissues." (PMID 36497364, 2022). "Accumulating evidence shows that cells become resistant to apoptotic processes when MUC1, MUC4, or MUC13 are expressed, implicating mucin expression in the malignant behaviors of carcinoma cells such as resistance to therapeutic modalities." (PMID 35410995, 2022). "Transmembrane mucins such as MUC1 and MUC16 are also thought to facilitate the metastasis of many carcinomas including pulmonary adenocarcinomas." (PMID 36497364, 2022). "Thus, inhibition of MUC1 activities could likely be an advantageous strategy in cancer therapy." (PMID 34206951, 2021). "Comparatively, Perepelyuk and colleagues synthesized a hybridized nanoparticle with a MUC1-aptamer for targeting delivery of miR-29b to NSCLC cells expressing MUC1, a transmembrane protein that is aberrantly expressed by cancer cells." (PMID 33803619, 2021). "It has been shown that the under-glycosylated form of MUC1 interacts with the multifunctional adaptor protein CIN85, fostering the invasiveness and migration of cancer cells." (PMID 33672244, 2021). "The current study aimed to design a theranostic platform based on superparamagnetic iron oxide nanoparticles-pyoverdine (SPION/PVD) conjugates bound to MUC1 aptamer (MUC1Apt) and loaded with doxorubicin (DOX) as an anti-cancer agent." (PMID 34158526, 2021). "In this review, we discuss the biological roles of the transmembrane mucins MUC1 and MUC16 in the context of hallmarks of cancer and current efforts to develop MUC1- and MUC16-targeted therapies." (PMID 34681277, 2021). "Expression of the clinically relevant cancer markers such as HER2 and MUC1 was also assessed in the context of the presented model of endometrial cancer." (PMID 33922995, 2021). "In this study, we investigated the expansion, differentiation, and suppressive function of MDSCs in MUC1-wild type (WT) and MUC1-null (MUC1KO) mice under cancer conditions." (PMID 34070449, 2021). "We here summarize the detailed tumorigenic roles of MUC1 and MUC16 in the context of cancer hallmarks." (PMID 34681277, 2021).
cancer (continued). "Using HAd5 vectors to express a combination of TAAs, such as CEA + brachyury + MUC1 and CEA + brachyury + mucin 1 (MUC1) + Her2 are also used to promote cancer vaccination." (PMID 33558455, 2021). "AFP can bind to MUC1 and MUC4 to synergistically promote cancer cells proliferation, migration and invasion." (PMID 33718192, 2021). "LY6E, MUC1, and FOS play important roles in immune escape and suppressive immune microenvironment in various types of cancers." (PMID 33144684, 2021). "Four bio-orthogonal click probes modified with trans-cyclooctene (TCO) were designed to enable the specific targeting of three cancer proteins (EGFR, EpCAM and MUC1) and one generic EV marker (CD63)." (PMID 34855021, 2021). "In cancer, MGL interacts with truncated O-glycans, namely the (s)Tn and (s)T antigen on glycan carriers like MUC1." (PMID 34638920, 2021). "MUC1 and MUC4 induced by IL-17RB upregulate expression of cancer stemness-related genes, such as SOX2, Nanog, Oct-4, and surface CD44 to facilitate sphere formation." (PMID 33082357, 2020). "In this work, we found IL-17RB upregulates MUC1 and MUC4 through NF-κB pathway to confer cancer cells resistance to gemcitabine." (PMID 33082357, 2020). "Finally, as MUC1-ST-induced macrophages are induced through interaction with Siglec-9 on monocytes, targeting the Siglec9/MUC1-ST interaction could effectively inhibit the production of the pro-cancer MUC1-ST-induced macrophages and impact on survival." (PMID 33149188, 2020). "In this direction, various glycoproteins such as prostate specific antigen (PSA), MUC16, aberrantly glycosylated MUC1 and CA19-9, including others, have been used historically to detect various cancers." (PMID 32075174, 2020). "Early cancer vaccines targeting over-expressed CAAs such as MART-1, MAGE, NYE-ESO-1, HER2, and MUC-1 demonstrated mediocre clinical results." (PMID 33193401, 2020). "Many studies have focused on MUC1 as an oncogene, not only in PDAC but also in different cancer types." (PMID 32745356, 2020). "Some other glycoprotein antigens such as MUC1 and KSA in epithelial cancers, PSMA in prostate cancers, and MUC16 in ovarian cancer are also abundantly expressed on other types of cancers and have also been a target for antibody‐inducing vaccines." (PMID 32594569, 2020). "Expectantly, studies have been designed to assess the predictive and prognostic importance of MUC1 in various forms of cancer, including invasive and metastatic breast cancer, with the aim of establishing a basis for improved diagnosis and the potential benefits MUC1 immunotherapy could afford." (PMID 32377198, 2020). "Contrary to this knowledge surrounding mucins in the PMT, MUC-4, and MUC-1 have been shown to play a crucial role in the EMT, where these contribute to the malignant transformation, invasiveness and metastatic potential of cancer cells." (PMID 33193109, 2020). "The aberrant form of MUC-1 is expressed in more than 80% of PDAC cases, which makes MUC-1 a good target for cancer immunotherapy." (PMID 35582441, 2020). "We investigated the role of MUC1, a gene which was one of the widely studied in cancer except for GBM, focusing on its anti-cancer mechanism by inhibition." (PMID 33106534, 2020). "A panel of four pan-cancer markers (EGFR, EPCAM, HER2, and MUC1) and three putative PC markers (GPC1, WNT2, and GRP94) were investigated individually and together in plasma-derived exosomes." (PMID 33297544, 2020). "Mucin-1 (MUC-1) is also known as polymorphic epithelial mucin and is a group of glycoproteins with high molecular mass that is overexpressed in human cancer cells including HCC cells." (PMID 32942580, 2020). "MUC1 and ITGAX were highly expressed in primary STS compared to some other types of cancer and they had a significant co-expression pattern in STS." (PMID 31739284, 2019).
cancer (continued). "Although MUC1 vaccine and PDE5 inhibitors has been proven safe when used as monotherapy in cancer patient the safety of the combination of these two immunologic strategies has not been previously evaluated." (PMID 31214178, 2019). "The ontological analysis revealed a role of these miRNAs in cancer progression, vascular invasion and cancer immune surveillance thought the regulation of DUSP1, PD-L1 and MUC1." (PMID 31164669, 2019). "Based on the success of these preclinical MUC1-CAR T cells, several clinical trials targeting MUC1 in several cancer types have begun." (PMID 30031396, 2018). "MassARRAY assays have been used to detect high methylation levels in the MUC1 promoter region in MDA-MB-453, a MUC1-negative cancer cell line." (PMID 30518424, 2018). "Here, we describe TSAs as proteins only expressed in cancer cells and mutated self-proteins (neoepitopes), and TAAs as unmutated self-proteins such as glycosylated proteins MUC1 and CEA or cancer testis antigens (CTAs)." (PMID 29740440, 2018). "The group designed two nano-complexes (MUC1 aptamer-NAS-24 aptamer-Graphene oxide and MUC1 aptamer-Cytochrome C aptamer-GO) that induce cell death in two cancer cell lines (MDA-MB-231 and MCF-7)." (PMID 29928493, 2018). "Chromosome 1 carries several amplified genes already reported in cancer such as ADAMTSL4, Histon2H gene family, MUC1 and TOMM20." (PMID 29844869, 2018). "Although MUC1 is known to confer resistance to apoptosis in response to several genotoxic drugs in PDA and other cancer cells, this is the first study that shows MUC1 blocks TGF-β induced apoptosis." (PMID 29467938, 2018). "Chimeric antigen receptors (CARs) targeting T cells to MUC1 were first developed and characterized by the Maher group using the SM3 antibody, which is highly selective for cancer MUC1 glycoforms, and the HMFG2 antibody, which also shows some selectivity." (PMID 29784646, 2018). "Immunization with MUC1, antigenic peptides, or pulsed DCs can induce MUC1-specific CTL responses in mice and human cancers." (PMID 29415891, 2018). "In support of a critical role for the MUC1/EGFR–ABCB1 axis in chemoresistance, targeted inhibition of EGFR by shRNA and erlotinib sensitizes cancer cells to chemotherapy in vitro and in vivo." (PMID 28796259, 2017). "For example, multiple studies provide direct evidence for the role of MUC1 in EMT process, which enable cancer cells acquire their invasive and metastasis potential." (PMID 29221212, 2017). "Vaccination with Stimuvax® stimulates immune-response-mediated, MUC1-specific cytotoxic T lymphocytes (CTL), which destroys cancer cells." (PMID 28346375, 2017). "Mucin 1 (MUC1) is a member of the mucoprotein family and abnormally expressed in various epithelial cells and malignant tumors." (PMID 28085094, 2017). "TG4010 is a cancer vaccine construct consisting of a recombinant, highly attenuated modified vaccinia Ankara (MVA) virus strain expressing both the human MUC1 and IL-2 genes (MVA-MUC1-IL-2)." (PMID 28116088, 2017). "Currently, a phase I/II clinical trial assesses CAR T-cells specifically targeting mucin 1 (MUC1) in solid tumors including GC, as its overexpression interferes with chemotherapy leading to refractory cancers." (PMID 28781967, 2017). "Overexpression of syndecan-1, MUC-1, and the putative cancer stem cell markers CD15, CD24, CD44, and CD133 has been documented on CSF floating cancer cells of BC patients with LM." (PMID 28399903, 2017). "Human cancer cell lines A431, MCF7 and KB known to express MUC1-TM protein were assessed for MUC1-ARF expression by western blot analyses." (PMID 27768738, 2016). "It has been shown previously that expression of mucin genes (including MUC1, MUC2, MUC3, MUC4 and MUC5AC) is regulated by DNA methylation at promoter regions in cancer cell lines." (PMID 27283771, 2016).